HPSE (heparanase)
Diseases named in the same sentence as HPSE in open-access papers (continued):
Sharing a sentence is not in itself a finding about the gene and the disease.
steatosis (1 paper, 2013). Increased lipid within the cytoplasm of cells. "In this study, in the HCV IRES-zebrafish model the remarkably increased expression in the steatosis marker genes, like heparanase, adiponecin, TGF-β, PDGF-α, HMGR may be related to the effect of core in hepatocytes." (PMID 23469178, 2013).
subarachnoid hemorrhage (1 paper, 2017). A serious neurological disorder characterized by intracranial hemorrhage into the subarachnoid space. "This study was designed to examine the association between heparanase expression and neuroinflammation during subarachnoid hemorrhage." (PMID 28720149, 2017). "However, the role of heparanase in neuroinflammatory response in subarachnoid hemorrhage (SAH) has not yet been investigated." (PMID 28720149, 2017).
systemic sclerosis (1 paper, 2021). A chronic disorder, possibly autoimmune, marked by excessive production of collagen which results in hardening and thickening of body tissues. "Heparanase was overexpressed in the systemic sclerosis sample compared to the control sample." (PMID 33567028, 2021).
thrombotic disorders (1 paper, 2012). "Here we demonstrate that sulodexide – a combination of GAGs composed of heparin-like (80%) and dermatan fractions (20%) that is currently used to treat thrombotic disorders and DN - is an effective HPSE inhibitor capable of preventing FGF-2-induced EMT in renal tubular cells." (PMID 23095131, 2012).
thyroid (1 paper, 2015). "To investigate the protein expression and differential protein profile among malignant, benign and normal thyroid lesions, we performed immunohistochemistry analyses for HPSE and HPSE2 on paraffin-embedded section." (PMID 26488476, 2015). "In conclusion, differential localization of HPSE2 in the thyroid follicle compared to DTC may suggest a role of heparanase in thyroid carcinogenesis." (PMID 26488476, 2015). "The present study demonstrated that both heparanases (HPSE and HPSE2) possibly play an important role in thyroid carcinogenesis and might also be used as a differential diagnosis for benign and malignant follicular tumors." (PMID 26488476, 2015).
urothelial carcinoma (1 paper, 2020). A malignant neoplasm derived from the transitional epithelium of the urinary tract (urinary bladder, ureter, urethra, or renal pelvis). "We investigated the role of heparanase, an enzyme activated by syndecan-1 in human urothelial carcinoma." (PMID 32471161, 2020). "The expression of heparanase protein was approximately 10% in normal urothelium but increased to approximately 30% in urothelial carcinoma samples (p < 0.05)." (PMID 32471161, 2020). "The aim was to establish heparanase as a target for molecular therapy in urothelial carcinoma." (PMID 32471161, 2020). "Heparanase induces invasion and autophagy in urothelial carcinoma." (PMID 32471161, 2020). "Heparanase may contribute to urothelial carcinoma cell survival and invasion." (PMID 32471161, 2020). "UROtsa, which has low expression of heparanae, has an IC50 of RK-682 about 2–3 times higher than that of urothelial carcinoma cell line, MGH-U3 cell line and T24 cell line which has high expression of heparanase." (PMID 32471161, 2020).
tumor (380 papers, 2002 to 2026). "Chemically modified heparin derivatives inhibit heparanase, an enzyme linked to tumor progression, angiogenesis, and metastasis." (PMID 40143176, 2025). "The achieved beneficial effects were associated with the newly acquired capability of heparanase-expressing CAR-T cells to split heparan sulfate proteoglycans to pave their way through the ECM-rich tumor stroma." (PMID 39996879, 2025). "HPSE is not only able to drive cancer growth and progression but can also support immune evasion, an emerging role associated with tumor-associated macrophages (TAMs)." (PMID 41301515, 2025). "mAb 9E8, directed against the KKDC peptide, was found to inhibit heparanase enzymatic activity, cell invasion, and tumor metastasis, the hallmark of heparanase function." (PMID 40940793, 2025). "This highlights the diverse functional roles of heparanase splice variants and their potential implications in tumor biology." (PMID 39202399, 2024). "Heparanase-1 also has a role in inflammation by facilitating the recruitment of immune cells in the context of cancer development, as is the case for the tumor-associated macrophages (TAM) that play an adverse role in pancreatic adenocarcinoma pathogenesis." (PMID 36680276, 2023). "Heparanase and Hpa2 not only exhibit opposite functions in terms of tumor growth but also in terms of the underlying mechanism." (PMID 37547889, 2023). "By univariate Cox regression analysis, we found that low levels of HPSE expression in tumor tissues correlated with a significantly increased risk of cancer-related death in patients with ESCC." (PMID 35840985, 2022). "Heparanase activity is strongly associated with major human pathological complications, including but not limited to tumour progress, angiogenesis and inflammation, which make heparanase a valuable therapeutic target." (PMID 36157032, 2022). "In this regard, heparanase activity plays a decisive role in tumor cell dissemination associated with the metastatic process and promotes tumor growth, angiogenesis, and metastasis." (PMID 35630523, 2022). "High expression levels of heparanase have been reported in several tumors and associated with tumor growth, invasiveness, metastasis, and poor prognosis." (PMID 35327524, 2022). "Heparanase over-secretion is observed in several solid tumours, sarcomas, haematological neoplasms, and is associated with aggressive tumour behaviour, a worse prognosis, and chemo-resistance." (PMID 34070058, 2021). "Elevated levels of heparanase were documented in an increasing number of human carcinomas and hematological malignancies, often associating with increased tumor metastasis and shorter survival rates." (PMID 33959505, 2021). "Heparanase is preferentially expressed in neoplastic tissues and associated with histone modifications that contribute to tumour metastasis and angiogenesis." (PMID 33922532, 2021). "The expression of heparanase in the tumor microenvironment is positively correlated with the aggressiveness of the tumor and is associated with poor prognosis." (PMID 34199150, 2021). "Many cancer types show increased levels of heparanase that promote resistance to chemotherapy, aggressive tumor progression and are therefore associated with poor prognosis." (PMID 34249755, 2021). "Heparanase is implicated in tumor growth, angiogenesis, and metastasis, and its expression is correlated with tumor aggressiveness." (PMID 33490732, 2021). "Heparanase strongly affects protein–HS interactions, whereas tumor-associated activated fibroblasts, endothelial cells, and immune cells exhibit increased heparanase activity." (PMID 33800172, 2021). "Macrophages are a cellular constituent of the tumor microenvironment and form a significant portion of tumour-associated immune cells, with heparanase playing a key role in their activation and function." (PMID 35069219, 2021).
tumor (continued). "Many of these interactions involve the HS chains of the HS-PGs, which explains the gene regulatory effects reported for nuclear heparanase and the association of HS-PG expression with tumour development." (PMID 33922532, 2021). "The high expression of HPSE in most malignancies exemplifies its role in cancer propagation, while its activity is closely linked to tumor progression and metastasis through the means of angiogenesis, autophagy, EMT and exosome biogenesis." (PMID 33809973, 2021). "Activity of the endo-beta-glucuronidase heparanase, capable of cleaving heparan sulfate (HS), is most often elevated in many types of tumors, associating with increased tumor metastasis and decreased patients’ survival." (PMID 33959505, 2021). "Activity of heparanase, responsible for cleavage of heparan sulfate (HS), is strongly implicated in tumor metastasis." (PMID 32038981, 2020). "The suppression of P-Akt and P-Erk by hinokitiol caused a significant downregulation of heparanase in the two tumor cell lines tested which resulted to a reduced tumor metastasis both in vitro and in vivo." (PMID 32132875, 2020). "With its multiple roles within the tumour microenvironment, heparanase has been demonstrated to regulate each of these hallmark features, in turn highlighting the need for heparanase-targeted therapies." (PMID 33256730, 2020). "Enhanced HPSE activity was previously associated with tumor invasiveness, but the cellular expression of heparanase in HNSCC was also associated with prolonged overall survival." (PMID 33585200, 2020). "Heparanase activity is strongly implicated in tumor metastasis, a consequence of remodeling the ECM underlying epithelial cells." (PMID 32038981, 2020). "In many malignancies, high expression of heparanase has been associated with an aggressive tumor phenotype." (PMID 33330449, 2020). "Heparanase has been strongly associated with important pathological processes including inflammatory disease and tumor metastasis, through its ability to promote various cellular functions such as cell migration, invasion, adhesion, and cytokine release." (PMID 31110966, 2019). "The data suggested that heparanase deficient NK cells were unable to degrade the tumor extracellular matrix and invade the tumor." (PMID 31850210, 2019). "Recently, the ability of heparanase to drive exosome secretion and alter exosome composition, has been linked to tumour progression." (PMID 31044520, 2019). "At the same time, exosomal protein cargoes were also altered by over-expressed heparanase, with increased package of proteins associated with an aggressive tumor phenotype." (PMID 31438991, 2019). "We recently reported that mice deficient in NK cell-heparanase exhibited reduced NK cell tumor infiltration, resulting in impaired clearance of B16F10 melanoma tumors and metastases." (PMID 31110966, 2019). "It is clear that heparanase has a profound role in the pathophysiology of a variety of different types of cancers; its increased expression is associated with greater tumor size, more angiogenesis, greater metastatic tendencies, and poor prognosis." (PMID 31850210, 2019). "The encouraging results from the preclinical studies corroborated the view that a causal link existed between heparanase inhibition and anti-tumor activity." (PMID 31362364, 2019). "A chronic state of aseptic inflammation is implicated in pancreatic ductal adenocarcinoma (PDAC), a tumor in which heparanase overexpression was linked with increased aggressiveness." (PMID 30413079, 2018). "Heparanase (HPA) is a tumor metastasis-associated gene that was cloned simultaneously by four laboratories in 1999." (PMID 29671088, 2018). "Through an enzyme-independent signaling function, mediated by the C-terminal domain, heparanase enhances the activation of protein kinases, ultimately increasing the transcription of genes associated with tumor progression, such as VEGF-A and VEGF-C." (PMID 30413079, 2018).
tumor (continued). "Heparanase (HPA) is ubiquitously expressed in various metastatic malignant tumors; previous studies have demonstrated that HPA was a potential tumor-associated antigen (TAA) for tumor immunotherapy." (PMID 29671088, 2018). "The key role of heparanase in inflammation-associated cancers is supported by its induction in several tumor-predisposing inflammatory disorders before the occurrence of malignancy." (PMID 30413079, 2018). "Initially, HPSE has been identified as an enzyme with glycosidase activity implicated in the invasion of tumor cells." (PMID 30487472, 2018). "To explore the potential mechanisms underlying the effect, we examined the expression of heparanase that has been found to be correlated to tumor growth and metastasis." (PMID 28505136, 2017). "Using gain and loss of function approaches we show that elevated heparanase levels suppress NK cell cytolytic activity to tumor cells in culture." (PMID 28969075, 2017). "Heparanase upregulation has been considered as one of the mechanisms underlying the induction of angiogenesis during repeated hypoxic exposures and tumor metastasis." (PMID 28720149, 2017). "As an endo-β-d-glycosidase which cleaves heparan sulfate (HS) side chains, heparanase is involved in cellular matrix metabolism associated with tumor metastasis, inflammation and angiogenesis." (PMID 28994624, 2017). "As CD62P mediated platelet adhesion was found to promote tumor growth, the finding of heparanase associated CD62P expression argues for a synergic activity of the molecules released from activated platelet in tumor development." (PMID 27129145, 2016). "Heparanase is associated with aggressive tumour behaviour including enhanced growth, angiogenesis, and metastasis." (PMID 27408707, 2016). "Heparanase levels remained stable in patients with poor treatment response and tumor progression, indicating its association with tumor burden." (PMID 27563824, 2016). "In fact, heparanase, which is rarely expressed in normal tissues, has been found highly expressed in several tumor types including RMSs and ESs, often associated with poor prognosis, and recently involved in chemoresistance." (PMID 27374103, 2016). "Recent studies have shown that heparanase of tumor tissues, blood, or urine is closely linked with an increasing number of human cancer types, including pancreatic, gastric, bladder, colon, and cervical cancer." (PMID 26569485, 2015). "HPSE expression is induced in all the principal types of human cancer and is often associated with reduced survival, increased tumor metastasis and higher density of microvessels." (PMID 26482785, 2015). "This property has linked heparanase with the promotion of a number of pro-tumor processes including angiogenesis, cell proliferation and invasion, inhibition of apoptosis, and metastasis." (PMID 25105093, 2014). "Heparanase is strongly implicated in tumour invasion and metastasis, because of its ability to cleave HS, chief polysaccharide component responsible for maintaining barrier properties of the ECM and basement membranes 5–7,9,12." (PMID 24286246, 2014). "Increased expression of heparanase is highlighted throughout the literature in a great number of tumor types, associated with angiogenic and metastatic potential of tumor cells." (PMID 24551591, 2014). "Enzymatic activity of heparanase (HPA) is implicated strongly in dissemination of metastatic tumor cells and cells of the immune system." (PMID 23442498, 2013). "MAP vaccine based on B-cell epitopes of HPSE is capable of alleviating HCC metastasis in vivo, mainly through inhibiting the HPSE activity and tumor associated angiogenesis, by virtue of the specific anti-MAP polyclonal antibodies." (PMID 23308126, 2013). "Heparanase (HPA), an endo-β-glucuronidase, is strongly implicated in cell dissemination associated with tumor metastasis and inflammation." (PMID 23442498, 2013).
tumor (continued). "Heparanase is an enzyme whose expression is associated with enhanced tumor growth, angiogenesis and metastasis." (PMID 26082317, 2013). "Heparanase that was cloned from and is abundant in the placenta is implicated in cell invasion, tumor metastasis, and angiogenesis." (PMID 23908827, 2012). "Our results show that the allele loss and reduced HPSE expression are indeed closely correlated with tumor progression and poor prognosis of HCC patients." (PMID 22952874, 2012). "Further, HS-degrading heparanase has been associated with tumor progression and poor patient outcome through remodeling of the tumor microenvironment." (PMID 23152853, 2012). "In experimental models, the cells expressing heparanase possess a high potential for extravasation of tumor cells in vascular vessels and are susceptible to develop a lung metastasis." (PMID 22363633, 2012). "While administration of heparinase III is associated with reduced tumor growth, heparanase activity is elevated in many hematological and solid tumors, correlating with poor prognosis and shorter postoperative survival rate." (PMID 23908791, 2011). "Tumor angiogenesis was closely related to the development and metastasis of ccRCC, and heparanase over-expression was associated with invasion and prognosis that was consistent with previous description." (PMID 22133010, 2011). "Cleavage of HS by the endo-β-glucuronidase heparanase (HPSE) is strongly implicated in cell dissemination associated with tumour metastasis." (PMID 21285983, 2011). "The cellular and molecular mechanisms underlying enhanced tumor growth by heparanase are only starting to be revealed." (PMID 23908791, 2011). "Heparanase expression has been linked to enhanced tumor aggressive behavior and poor prognosis in a number of cancers." (PMID 19305494, 2009). "Heparanase activity has been correlated and causally associated with the metastatic potential of tumor-derived cells, attributed to enhanced cell dissemination as a consequence of HS cleavage and remodeling of the ECM barrier." (PMID 19360105, 2009). "Expression of the heparanase gene is associated with the invasion and metastatic potential of a variety of tumor-derived cell types." (PMID 18647407, 2008). "In addition to its roles in platelet function and wound healing, heparanase has been implicated in various pathological processes, including inflammation, angiogenesis, metastasis, and tumor growth." (PMID 39202399, 2024). "Heparanase expression is often associated with enhanced tumor aggressiveness and chemoresistance." (PMID 37091070, 2023). "Function of HPSE is strongly associated with major human pathological complications, evidenced by that various literatures have linked overexpression of HPSE to enhanced tumor growth, metastasis and poor prognosis." (PMID 36157032, 2022). "The importance of the HS chains of Sdc-1 in the prevention of tumour spread is exemplified by the heparanase-mediated loss of HS in Sdc-1, which enhances histone acetyltransferase activity and results in gene expression to drive an aggressive tumour cell phenotype." (PMID 33922532, 2021). "Given the causal role of heparanase in tumor progression in tissues in which cancer-related inflammation typically occurs, (i.e., gastrointestinal tract, pancreas, liver), it is conceivable that inflammation-induced heparanase is involved in coupling inflammation and cancer." (PMID 34220822, 2021). "Similarly, in normal breast epithelium, heparanase is undetected, but in breast malignancy, its expression elevates, which is linked with larger tumour size and aggressiveness." (PMID 34070058, 2021). "Suppression of heparanase was associated with a significant decrease in tumour invasion." (PMID 34070058, 2021).